MKRN2 (makorin ring finger protein 2)
Description:
E3 ubiquitin ligase catalyzing the covalent attachment of ubiquitin moieties onto substrate proteins (By similarity). Promotes the polyubiquitination and proteasome-dependent degradation of RELA/p65, thereby suppressing RELA-mediated NF-kappaB transactivation and negatively regulating inflammatory responses (By similarity). Plays a role in the regulation of spermiation and in male fertility (By similarity).
Synonyms: RNF62; HSPC070
Tractability: PROTAC: ubiquitination databases record sites on it; its protein half-life has been measured.
Gene: Protein-coding gene on chromosome 3 (12,557,020 to 12,586,208, forward strand). Ensembl gene ENSG00000075975.
Subcellular location: Cytoplasm; Nucleus
Subcellular location (Human Protein Atlas): Cytosol; Nucleoplasm
Gene Ontology:
Molecular function: protein binding; RNA binding; ubiquitin protein ligase activity; metal ion binding
Biological process: DNA-templated transcription; negative regulation of inflammatory response to antigenic stimulus; negative regulation of non-canonical NF-kappaB signal transduction; phosphatidylinositol 3-kinase/protein kinase B signal transduction; positive regulation of transcription by RNA polymerase II; protein ubiquitination; ubiquitin-dependent protein catabolic process; protein polyubiquitination
Cellular component: cytoplasm; nucleus
Genetic constraint (gnomAD): Loss-of-function variants: 30 observed, 42.85 expected, observed/expected ratio (o/e) 0.7, 90% interval 0.52 to 0.95. The upper end of that interval is the gene's LOEUF score, 0.95, which puts it in group 4 of 6, group 1 being the genes least tolerant of losing a copy. Missense variants: 508 observed, 537.31 expected, observed/expected ratio (o/e) 0.95, 90% interval 0.88 to 1.02. Synonymous variants: 198 observed, 195.65 expected, observed/expected ratio (o/e) 1.01, 90% interval 0.9 to 1.14.
Homologues: Orthologues: macaque MKRN2 (99% identical), chimpanzee MKRN2 (98% identical), dog MKRN2 (94% identical), rabbit MKRN2 (89% identical), rat Mkrn2 (89% identical), mouse Mkrn2 (88% identical), guinea pig MKRN2 (85% identical), pig MKRN2 (83% identical), tropical clawed frog mkrn2 (64% identical), zebrafish mkrn2 (58% identical), Caenorhabditis elegans lep-2 (33% identical), Drosophila melanogaster Mkrn1 (31% identical), and 3 more. Paralogues in human: MKRN1 (45% identical), MKRN3 (34% identical).